IL1B (interleukin 1 beta)
Diseases named in the same sentence as IL1B in open-access papers (continued):
Sharing a sentence is not in itself a finding about the gene and the disease.
infection (continued). "Attenuating NF-κB activation is critical because it induces the transcription of pro-inflammatory genes, including those encoding cytokines like TNF-α and interleukin-1 beta (IL-1β), which are pivotal in immunological and inflammatory responses, particularly during infection and trauma." (PMID 39599671, 2024). "Thus, we quantified inflammasome-associated cytokines, IL-1β and IL-18, in cecal and colonic tissues of the infected mice during the first 4 days of the infection." (PMID 39298531, 2024). "Moreover, the levels of pro-inflammatory cytokines IFN-γ, TNF-α, IL-1β, and IL-6 were significantly lower in the Δα-amy group, further suggesting that infection with Δα-amy cysts hardly caused remarkable inflammatory damage to intestinal tissues." (PMID 38087373, 2023). "The wild-type mice showed high numbers of neutrophils at the site of infection in the ear, that may be due to high IL-1β compared to deficient NLRP3 inflammasome mice." (PMID 37276232, 2023). "A reduction in the proinflammatory cytokines IL-1β, IL-6, and IL-8 produced by Th1 cells may increase the risk of infection and virus reactivation." (PMID 36904156, 2023). "Infection of the CNS and neuronal loss after ischaemic brain damage are both aggravated by IL‐1β." (PMID 37031383, 2023). "This strong IL-1β inflammatory response may coincide with the previously conducted study where koi were found to be susceptible to both genogroups I or IIa infections." (PMID 37465154, 2023). "However, we found decreased IL-1β secretion early during infections with C1-deficient vaccinia, consistent with a pro-inflammatory role also observed from cell-based reporter assays." (PMID 36909515, 2023). "Studies have shown that IL-1β secretion is a factor that further causes inflammatory cytokine storms, and IL-1β secretion was dependent on the decrease in the net concentration of canagliflozin after infection." (PMID 37685881, 2023). "This suggests that IL-1β may increase the bladder mucosa’s susceptibility to infection and enhance UPEC colonization." (PMID 37111409, 2023). "Indeed, in high-infected larvae, uncontrolled parasitaemia induces a strong pro-inflammatory response, defined by an overall induction of TNFα and IL1β in both immune and endothelial cells, associated with susceptibility to the infection." (PMID 36829432, 2023). "In addition, M1-, and to a lesser extent M2-differentiated caspase 1-deficient THP-1 cells also produced IL-1β in response to infection." (PMID 36851476, 2023). "Additionally, Ad-IL8 infection increased the mRNA levels of inflammatory genes such as Adgre1 (the gene encoding F4/80), Tnfa, and Il1b in the livers of HFD-fed mice." (PMID 37895168, 2023). "In addition, targeting the NLRP3 inflammasome (e.g., MCC950) or downstream IL1β (e.g., Canakinumab) has raised concerns over increased susceptibility to pathogenic infection and long-term side effects." (PMID 35054783, 2022). "Guided by our transcriptomic results indicating that a critical subset of inflammatory mediators are controlled by CASP11, we measured levels of CXCL1, IL-1β, and IL-6 by enzyme-linked immunosorbent assay (ELISA) in lung homogenates from infected animals at 2 and 4 d after infection." (PMID 35588457, 2022). "High levels of IL-1β were detected in bronchoalveolar lavage fluid and blood plasma of patients with lung injury caused by coronavirus or other respiratory viruses (such as adenovirus or influenza virus) infections." (PMID 36248872, 2022). "Thus, IL1-β is an essential mediator of early infection responses and a critical cytokine linked to inflammation." (PMID 35625510, 2022). "Besides, the levels of proinflammatory cytokines interleukin 6 (IL-6) and interleukin 1 beta (IL-1β) were higher during the resolution of infection, in peritoneal cavity or plasma of Alkbh5-deficient mice than WT littermates after a mild CLP." (PMID 35764614, 2022).
infection (continued). "IL-1α and IL-1β are key players in the innate immune system; IL-1α is implicated in the initiation/maintenance of the immune response to infection; and IL-1β is produced by activated macrophages, T lymphocytes, and NK cells and is essential for the initiation of the immune response." (PMID 35431938, 2022). "We hypothesize that these signs are associated with or caused by elevated proinflammatory cytokines such as IL-1β, which is processed by activated inflammasomes during the infection." (PMID 35173184, 2022). "However, several studies in mice have shown an increased risk of infection in response to complete blockage of endogenous IL-1β, as well as in studies of IL-1R1-deficient mice." (PMID 35632584, 2022). "In contrast, GSDMD deficiency would inhibit the release of IL-1β and IL-18 after the infection." (PMID 36311722, 2022). "Our results confirmed that LPS infection indeed caused acute inflammatory damage in mice lung, accompanying with the enhancement of IL-1β contents and the activation of the NLRP3 inflammasome in lung tissue and macrophagocyte, all of which were remarkably ameliorated by PR treatment." (PMID 36046826, 2022). "Taken together, the mouse and fish infection models demonstrate that the abuandance of succinate and inosine are strongly associated with the expression of IL-1β, C3 expression and animal mortality, which can be altered by exogenous supplmentation of metabolites." (PMID 36026499, 2022). "In TB, pyroptosis in Mtb-infected macrophages not only releases several pro-inflammatory mediators, including high mobility group protein (HMGB1) and interleukin-1beta (IL-1β), but also spreads the Mtb bacteria, aggravating the pathologic process and increasing the risk of infection." (PMID 35528511, 2022). "In addition, the following studies suggest that some of the virulence factors encapsulated in MVs can cause violent IL-1β release through the cell pyroptosis pathway to prevent pathogen infection." (PMID 36619996, 2022). "Notably, the cytokine IL-1β was the first parameter to be linked to infection-induced premature labor." (PMID 35622593, 2022). "As during evolution, trauma and infection presumably were among the leading causes of death, it is conceivable that complex and redundant mechanisms evolved that tightly regulate the biosynthesis, maturation, and secretion of IL-1β." (PMID 36105198, 2022). "The IL-1β mRNA level was significantly increased in the spleen after GNAstV infection, which may initially inhibit GNAstV infection, but excess production of IL-1β may cause splenic lesions." (PMID 33647718, 2021). "Interestingly, NLRP3 deficiency resulted in higher levels of IL-1β in the brain later in infection, suggesting a regulatory role for NLRP3 in modifying caspase-1 activity rather than simply increasing IL-1β activation in response to an immune stimulus." (PMID 33524073, 2021). "Importantly, pharmacologic inhibition of the inflammasome and IL-1β pathways reduced cytokine levels and mortality and partly restored infection control in iron-treated ferritin-deficient mice." (PMID 34236052, 2021). "Notably, LF pre-infection treatment (unwashed) resulted in decreased expression of IL1B and IL6 transcripts, proinflammatory cytokines associated to the cytokine storm." (PMID 33498631, 2021). "Although IL-1β plays an important role in pathogen infection, overexpression of IL-1β may also cause severe gastric inflammasome to the host." (PMID 34899717, 2021). "In addition, neutrophil influx into the bite site at earlier stages of infection was required for the induction of vital bite-associated genes such as IL-1β, CCL2, CCL7, and CCL12." (PMID 34073501, 2021). "Moreover, the use of canakinumab, a human monoclonal antibody targeted at IL-1β, was also associated with increased susceptibility to infection." (PMID 34831246, 2021).
infection (continued). "Likewise, the levels of pro-inflammatory cytokines implicated in CA16 infection, namely, IL-1β, IL-6, IL-18, and IFN-γ, were found to be significantly elevated in infected hSCARB2 transgenic mice." (PMID 33882964, 2021). "Furthermore, we suggest that extrinsic and intrinsic apoptosis caused by MO infection are associated with increased expression of proinflammatory cytokines, including IL-1β, IL18, and TNF-α." (PMID 34678131, 2021). "The animal model of chronic airway infection differs significantly from those used in prior studies of IL-1α and IL-1β during A. fumigatus infection in which mice were infected with either a high dose of conidia, or were immunosuppressed to render them susceptible to infection." (PMID 34322116, 2021). "IL-1β knockout mice exhibit increased susceptibility to infection in an intranasal model of HSE." (PMID 33524073, 2021). "Mice deficient in IL-1β or IL-1 receptor type I (IL-1R1) have been shown to be highly susceptible to infection with MTB, as reflected by decreased survival time, increased bacterial burden in lungs and bronchoalveolar lavage fluid (BALF) and extensive pulmonary necrosis." (PMID 33503864, 2021). "Herein, the relative expression fold change values of IL-4 and IL-13 were next to those of IL-23, IL-1β, and IL-22, suggesting that a higher expression of Th2-associated cytokine genes coincided with the increased percentage of Th2 cells after infection with intravenous injection." (PMID 33441700, 2021). "Similarly, during the early stages of infection of GF zebrafish with Vibrio anguillarum, the expression of genes encoding interleukin 1 beta (IL-1β), toll-like receptor 4 (TLR4), NF-κB, and transferrin (TRF) decreased significantly." (PMID 33147801, 2020). "However, consistent with previous studies of non-M1 covS mutant GAS, the release of the inflammatory cytokine IL-1β, a hallmark of clinical invasive infection, was only significantly increased in response to 5448AP infection in vitro and in vivo." (PMID 33585270, 2020). "For that purpose, we verified whether BMDMs deficient in components of the pathway were able to release IL-1β, IL-1α, and IL-18 in the same manner as WT cells in response to the infection by live tachyzoites." (PMID 32523898, 2020). "In addition, the pretreatment with Ab extract leads to a complete control of bacteremia 24 h post infection, associated with an augment in NO, and a significant decrease in IL-1β and TNF-α levels in septic animals." (PMID 32714320, 2020). "IL-1β, expressed by monocytes, is used as a marker for general inflammation caused by infection." (PMID 32664205, 2020). "In early control of cranial biofilm infection spread, TLR2 is associated with macrophage IL-1β pro-inflammatory cytokine production, but this signaling was insufficient to clear infection, perhaps due to established infection manipulation of the macrophage response." (PMID 33542723, 2020). "The CANTOS trial provided favorable evidence that inhibition of the IL-1β/IL-6 signaling cascade led to a significant reduction in cardiovascular risk, independent of a lipid-lowering effect, but with an increased risk of serious infection." (PMID 33614738, 2020). "Similarly, infection of these cells with RSV yielded a drastic loss of IL-1β production since NLRP3 and ASC are required for RSV-mediated inflammasome activation." (PMID 32854254, 2020). "A quadratic model was fitted, and in addition to time from infection, we identified age as a factor associated with relative IL-1β transcription; as observed for constitutive transcription, both the young and older cats showed a more intense increase after infection than the middle aged cats." (PMID 33121170, 2020). "Since chMIF was secreted by DT40 and bursal cells upon vvIBDV infection, we also investigated whether the supernatant of the infected cells could cause upregulation of IL-1β and IL-18 in response to vvIBDV infection." (PMID 31632367, 2019).
infection (continued). "Conversely, infection experiments using candidalysin-deficient C. albicans showed that candidalysin crucially contributed to the capacity of this fungus to induce maturation and secretion of IL-1β from primary macrophages." (PMID 30622184, 2019). "A wide variety of biologic effects associated with infection and inflammation are caused by the assembly of inflammasome complex, which activates caspase-1, and causes the secretion and maturation of proinflammatory cytokines IL-1β and IL-1." (PMID 31390729, 2019). "In addition, differences in host susceptibility to IL-1β, IL-18, and caspase-1-deficient mice during infection have been reported." (PMID 29616195, 2018). "Our model also revealed a robust inflammatory response at the infection site characterized by the upregulation of genes encoding major pro-inflammatory cytokines, such as Il1b, Tnfa, Il22, several chemokines and chemokine receptors, complement factors, and pattern recognition receptors (PRR)." (PMID 30143654, 2018). "Notably, an infection in primed macrophages was unable to activate caspase-1 or IL-1β and mice deficient in the key inflammasome components ASC and caspase-1/11 showed no change in their disease phenotype." (PMID 29487860, 2018). "In previous studies using P. aeruginosa infection models, blocking the actions of some of these markers (e.g., MCP-1, MIP-1β, and IL-1β) was linked to a beneficial outcome for the resolution of infection, with greater bacterial clearance and diminished tissue damage." (PMID 29483116, 2018). "IL-1B expression increases the expression of factors adhered to vascular endothelial cells that cause the leukocytes to extravagate to the site of infection and resets the temperature regulation center in the hypothalamus which leads to increased body temperature." (PMID 30320011, 2018). "SGA may be linked to lower levels of certain cytokines (e.g., interleukin 1 beta), which are involved in the inflammatory response in infection." (PMID 30562348, 2018). "Genotyping of IL-1RN (VNTR) and IL-1β 511C/T polymorphism may be beneficial to predict the immune defense against infection and a prolonged Th1 cell-mediated immune response." (PMID 29849489, 2018). "Finally, inflammatory mediators associated with continuing infection, e.g., GM-CSF, predispose for IL-1β production over T1-IFNs by iM and iDC." (PMID 28424682, 2017). "However, mice deficient for IL-1β, IL-18 or caspase 1 were as susceptible as wild-type mice to both blood stage and sporozoite PbA-infection." (PMID 28448579, 2017). "It is possible that weight gain in B. burgdorferi‐infected animals was due to events such as IL‐1β downregulation or a shift in their microbiota, but it is equally possible that factors like reduced physical activity due to infection‐associated discomfort or fatigue contributed to this phenotype." (PMID 27794208, 2017). "Besides, the polymorphism of IL-1 (IL-1B-31*C/-511*T and IL-1RN*2/2*) is associated with the reduced production of gastric acid and gastratrophia with infection of H. pylori." (PMID 28360909, 2017). "Overall, EhLPPG induced the strongest infection-and treatment-specific increases in mRNA encoding protective cytokines (Il-1β, 2.7 ± 0.47 [p = 0.018]; NOS2, 4.9 ± 0.3 [p > 0.0001]); however, it had only a moderate effect on mRNA encoding non-protective cytokines (Il-10, 2.5 ± 1.2 [ns])." (PMID 28842620, 2017). "However, we found that the levels of Gro-α, IL-23, MCP-1, IL-17 and IL-1β were significantly increased in Nod2-deficient mice in comparison to wild type controls at 4 h post-infection." (PMID 29234083, 2017). "Consequently, AP-3 deficient DCs hyposecrete IL-1β and IL-18 in response to phagocytosed stimuli, and AP-3 deficient mice succumb to infection by a bacterial pathogen." (PMID 29253868, 2017).
infection (continued). "More recently, it has also been reported that abortive infection of HIV-1 in CD4pos T cells induces an inflammatory programmed cell death (i.e. pyroptosis) caused by the release of pro-inflammatory cytokines including IL-1β." (PMID 27599995, 2016). "More recently, it has become clear that IL-1β is also of critical importance for host control of TB infection given that mice deficient in IL-1R or its adaptor MyD88 succumb rapidly to low-dose aerosol infection with TB." (PMID 27034588, 2016). "Decreased MAC formation may be associated with reduced IL-1β production through activation of caspase 1, followed by inflammasome formation in the recipients; this might further contribute to the high risk of infection in these recipients." (PMID 27063552, 2016). "Infection of larvae expressing a RNA encoding a fusion between zebrafish pro-IL-1β and GLuc (zfiGLuc) resulted in increased luciferase activity independently of Asc (assayed in Asc-deficient fish) and caspase-1 activity (assayed in the presence of caspase-1 or pan-caspase inhibitors)." (PMID 27363812, 2016). "A recent study reported that Ft-specific IgM produced by B1a B cells was significantly reduced in Il-1b/-, Il-1b-/-/Il-1a-/-, or Il-1r1-/- mice compared to C57BL/6J wildtype or Il-1a-/- mice and implicated as an explanation for susceptibility of IL-1β-deficient mice to pulmonary Ft LVS infection." (PMID 27926940, 2016). "Infection with a high dose of the intracellular parasitic protozoan Leishmania major induces a sustained hyperalgesia in susceptible BALB/c mice accompanied by up-regulation of the pro-inflammatory cytokines IL-1β and IL-6." (PMID 26913003, 2016). "Because activation of the inflammasome leads to production of IL-1β and escalation of inflammation for enhanced pathogen clearance, counter measurements to this type of pathway appear to be vital for the survival of and successful infection by A/E pathogens." (PMID 26332984, 2015). "However, D39ΔPLY infection caused a reduced level of capase-1 p10 and the expression of IL-1β and IL-18 was also less elevated in the brains of D39ΔPLY-challeged mice than in D39-challenged mice." (PMID 26683708, 2015). "The negative impact that such a response could have is considerable, as recent evidence suggests that genetic variants of IL-1α and IL-1β may exert a substantial impact on the susceptibility of H1N1pdm09 infection." (PMID 25831059, 2015). "IL-1β, which also signals via MyD88, has been proposed to be dispensable for host defense as mice deficient in the Nlrp3 inflammasome did not exhibit increased susceptibility to S. pyogenes in an intraperitoneal infection model." (PMID 25756897, 2015). "In silico data using the GP63-cleavage motif indicated a possible GP63-mediated processing of inflammasome or inflammasome-associated proteins, including NLRP3 and pro-IL-1β, which we were able to confirm in infection experiments of both murine BMDMs and human THP-1 macrophages." (PMID 26114647, 2015). "Long-term examination of the infected il1b morphants revealed that loss of il1b prevented formation of the lesions that were often detected in the rostral part of the notochord after infection (lesions were found in one out of 12 il1b morphant fish and seven out of 11 scrambled morpholino fish)." (PMID 24973754, 2014). "These exciting results clearly indicate that the response of ‘arthritic’ osteoblasts to RRV infection differs from normal osteoblasts; they are more susceptible to infection possibly through delayed type I IFNs response and produce higher levels of IL-6, IL-1β, CCL2 and TNF-α." (PMID 25407789, 2014). "It is now well established, in rodents, that systemic inflammation such as that caused by injury, surgery or infection, induces de novo CNS expression of IL-1β transcripts and synthesis of IL-1β protein in circumventricular organs, the cerebro vasculature and in brain parenchymal microglial cells." (PMID 25124807, 2014).